SIRT1 (sirtuin 1)
Diseases named in the same sentence as SIRT1 in open-access papers (continued):
Sharing a sentence is not in itself a finding about the gene and the disease.
papillary thyroid cancer (5 papers, 2016 to 2023). "Hypermethylation of the HIC1 promoter and aberrant expression of HIC/SIRT1 may be useful for assessing the risk of developing thyroid papillary carcinoma and may be a novel therapeutic target." (PMID 27793057, 2016). "We hypothesized that HIC1 promoter methylation would cause abnormal expression of HIC1/SIRT1, thereby enhancing the development and progression of papillary thyroid carcinoma." (PMID 27793057, 2016). "Based on the insights of physiological VD/SIRT1/FOXO3a interplay in immune cells, a similar experimental setup was carried out in papillary thyroid cancer cells." (PMID 30271381, 2018). "Wu et al36 verified that restoration of HIC1 expression via 5‐Aza treatment reduced SIRT1 expression and cell propagation, and led to senescence, cell cycle arrest and apoptosis in thyroid papillary carcinoma." (PMID 30039914, 2018). "Immunohistochemical analysis of SIRT1 expression confirmed low levels of nuclear protein in normal thyroid tissues, and staining in both the nucleus (dominant) and cytoplasm in papillary thyroid carcinomas." (PMID 27793057, 2016). "A negative correlation between the mRNA expression levels of HIC1 and SIRT1 was observed in the papillary thyroid carcinomas." (PMID 27793057, 2016). "The expression level of nuclear SIRT1 in papillary thyroid carcinomas was significantly greater than the adjacent normal thyroid tissues." (PMID 27793057, 2016). "HIC1 protein expression in the papillary thyroid carcinomas (0.42 ± 0.07) was lower than in the adjacent normal tissues (0.94 ± 0.11; p < 0.01) and the inverse was true for SIRT1 protein expression." (PMID 27793057, 2016). "Similarly, the relative SIRT1 mRNA expression in papillary thyroid carcinomas (2.27 ± 0.12) was significantly higher than in the paired normal thyroid tissues (0.32 ± 0.06)." (PMID 27793057, 2016). "Therefore, we assessed the level of methylation in the HIC1 promoter and the mRNA and protein expression levels of HIC1 and SIRT1 in human thyroid papillary carcinoma and tumor adjacent control tissues." (PMID 27793057, 2016). "In papillary thyroid carcinoma, it is likely that reduced expression of the HIC1 gene contributes to upregulation of SIRT1 expression." (PMID 27793057, 2016). "Moreover, T-helper cells of HC and papillary thyroid cancer cell line BCPAP were incubated with 1,25(OH)2D3 and/or SIRT1 inhibitor Ex-527 in order to elucidate SIRT1- dependent vitamin D effects on cell proliferation and FOXO3a gene expression in vitro." (PMID 30271381, 2018). "Consistent with the mRNA results, there was also a negative correlation between HIC1 and SIRT1 protein expression in the papillary thyroid carcinomas (p < 0.05)." (PMID 27793057, 2016). "Aberrant expression of HIC1/SIRT1 and hypermethylation of the HIC1 promoter may be critical for the development and progression of papillary thyroid cancer." (PMID 27793057, 2016). "In papillary thyroid carcinoma, the methylation and expression patterns of HIC1 have not yet been described and it is unclear whether the HIC1/SIRT1 pathway is involved in the development and progression of disease." (PMID 27793057, 2016).
prediabetes (5 papers, 2021 to 2026). "Metformin increased sirtuin 1 protein expression and mTOR expression in peripheral blood mononuclear cells from subjects with prediabetes; sirtuin 1 expression was also induced in patients with carotid artery atherosclerosis." (PMID 33801956, 2021). "miR-27 was up-regulated in obese prediabetes, targeting regulators of oxidative stress and apoptosis such as BCL2, BMI1, FOXO3, and suppressing SIRT1, thereby amplifying IL-6 production." (PMID 41400625, 2025).
Salmonella Infections (5 papers, 2018 to 2024). Infections with bacteria of the genus SALMONELLA. "Since SIRT1 and SIRT3 played an immunemodulatory role in Salmonella infection, we investigated whether Salmonella infection is associated with a shift in macrophage polarization status." (PMID 39693143, 2024). "In KEGG pathway analysis, it can be found that ESR1 is mainly related to endocrine resistance, the cancer signaling pathway, the estrogen signaling pathway, and Epstein-Barr virus infection, while SIRT1 is mainly related to the FoxO signaling pathway and Salmonella infection." (PMID 38835801, 2024). "For the KEGG pathways, SIRT1 was significant more positively correlated with valine, leucine, and isoleucine biosynthesis, and Salmonella infection, while it was significant more negatively correlated with pentose phosphate pathway and biosynthesis of cofactors." (PMID 36299860, 2022). "Together, this study highlights the complex and multifaceted nature of host–pathogen interactions, and the need for further research to fully understand the role of SIRT1 and SIRT3 in the context of Salmonella infection." (PMID 39693143, 2024). "Overall, our study highlights the crucial role of SIRT1 and SIRT3 in governing the host immune-metabolic shift during Salmonella infection, which in turn is vital for maintaining Salmonella metabolism." (PMID 39693143, 2024). "This indicates the possible role of SIRT1 and SIRT3 in the regulation of cytokine production upon Salmonella infection." (PMID 39693143, 2024). "SIRT1 expression showed negative correlation with Proteasome, Oxidative phosphorylation, and Salmonella infection." (PMID 38521905, 2024). "Previous reports have elucidated the role of SIRT1 and SIRT2 pertaining to Salmonella infection." (PMID 39693143, 2024).
soft tissue sarcoma (5 papers, 2013 to 2021). A malignant neoplasm arising from muscle tissue, adipose tissue, blood vessels, fibrous tissue, or other supportive tissues excluding the bones. "In the present study, we analyze the expression of TOP2A and SIRT1 in a large and well-characterized cohort of high-risk soft tissue sarcoma patients with a long-term follow-up and correlate our findings with clinical tumor characteristics and survival data." (PMID 34638362, 2021). "TOP2A and SIRT1 showed distinct expression patterns in different high-risk soft tissue sarcoma subtypes." (PMID 34638362, 2021). "In this study, we analyzed the expression of TOP2A and SIRT1 in a well-characterized cohort of high-grade soft tissue sarcoma patients using tissue microarrays and immunohistochemistry." (PMID 34638362, 2021). "Strengths of this study were the analysis of TOP2A and SIRT1 on a large patient cohort of high-grade soft tissue sarcomas." (PMID 34638362, 2021). "This study has also demonstrated a significant correlation between the expression of SIRT1 and β-catenin, in addition to the prognostic role of SIRT1 in soft-tissue sarcomas." (PMID 24019980, 2013). "Moreover, SIRT1- and DBC1-related pathways may be involved in the progression of soft-tissue sarcomas and SIRT1- and DBC1-related pathways may provide targets for novel therapeutic approaches for soft-tissue sarcomas." (PMID 24019980, 2013). "In this study, nuclear expression of SIRT1 was an independent prognostic indicator for OS and EFS in soft-tissue sarcoma patients." (PMID 24019980, 2013). "However, there have been no previous reports examining the prognostic significance of the expression of SIRT1 and DBC1 in soft-tissue sarcoma." (PMID 24019980, 2013). "Therefore, we investigated the prevalence and prognostic significance of SIRT1 and DBC1 expression in soft-tissue sarcoma patients." (PMID 24019980, 2013). "In conclusion, this study is the first to demonstrate that the expression of SIRT1 and DBC1 could be used as novel prognostic indicators of soft-tissue sarcoma." (PMID 24019980, 2013). "When separately analyzed the soft-tissue sarcomas according to the tumor stage (stage I and II versus stage III and IV) and histological grade (grade 1 versus grade 2 and 3), nuclear expression of SIRT1 predicted sorter OS and EFS regardless of the tumor stage or histological grade." (PMID 24019980, 2013).
viral myocarditis (5 papers, 2023 to 2026). Myocarditis that is caused by an infection with a viral agent. "The mRNA level of SIRT1 in the blood samples from children with viral myocarditis was significantly lower when compared to healthy volunteers." (PMID 38256030, 2024). "Researchers argue that miR-217 and miR-543 inhibition may attenuate viral myocarditis by impending the apoptosis of cardiomyocytes and preventing the inflammatory response and oxidative stress by targeting SIRT1." (PMID 38256030, 2024). "Similarly, the inhibition of miR-543 reduced inflammation and provided protection against viral myocarditis through upregulation of sirtuin-1 (SIRT1)." (PMID 38132140, 2023).
acute respiratory distress syndrome (4 papers, 2015 to 2025). Progressive and life-threatening pulmonary distress in the absence of an underlying pulmonary condition, usually following major trauma or surgery. "Nrf2 is in a close mechanistic relationship with sirtuin 1 and NK-κB, whose close coordination in the protection from acute lung disease and acute respiratory distress syndrome has been raised as possible." (PMID 34356384, 2021). "Another study reported that miR-199a aggravates LPS-induced inflammatory response via targeting SIRT1 in acute respiratory distress syndrome (ARDS)." (PMID 30918470, 2019).
adenoma (4 papers, 2012 to 2025). A neoplasm arising from the epithelium. "High levels of SIRT1 expression are found in normal colonic mucosal tissues and benign adenomas, whereas a reduction in SIRT1 expression is seen in adenocarcinoma, metastatic tissues, and advanced stage IV tumors." (PMID 40567502, 2025). "When we compared tumor size distribution between SIRT1−/− and SIRT1+/+ mice we found that only 2% of adenomas in SIRT1−/− mice were larger than 1.0 mm in diameter, whereas 12% of tumors in the control group reached this size (p = 0.0076)." (PMID 23799088, 2013). "Mammary glands from 6 week old female Sirt1Y/Y mice carrying the MMTV-PyMT transgene contained sites of hyperplasia/adenoma similar to those found in Sirt1+/+ mice suggesting that SIRT1 has little effect on the very early stages of tumor initiation." (PMID 24278473, 2013). "Our findings that the lack of SIRT1 decreases the number of basal crypt cells expressing the active form of β-catenin and that SIRT1-inhibition reduces β-catenin mediated transcriptional activity in vitro, suggest that SIRT1 may indeed promote adenoma formation through increased Wnt signaling." (PMID 23799088, 2013). "We first analyzed β-catenin expression in adenomas of APC+/min mice and observed increased expression levels and nuclear accumulation of β-catenin regardless of the intestinal SIRT1 deletion." (PMID 23799088, 2013).
allergic asthma (4 papers, 2019 to 2023). A asthma with a basis in a pathological type I hypersensitivity reaction. "This study investigates the total serum IgE, FoxO1, and Sirtuin 1 (SIRT1) gene expressions in HDM-allergic asthma patients." (PMID 37987301, 2023). "Moreover, the results recommend further studies on the use of FoxO1 and SIRT1 in the treatment of HDM-allergic asthma." (PMID 37987301, 2023). "There was a negative correlation with SIRT1 in HDM-allergic asthma patients who had not received immunotherapy treatment." (PMID 37987301, 2023).
allergic rhinitis (4 papers, 2020 to 2025). Inflammation of the nasal mucous membranes caused by an IgE-mediated response to external allergens. "In a study involving ovalbumin (OVA)-induced allergic rhinitis mice, researchers administered the SIRT1 agonist resveratrol (RSV)." (PMID 39081309, 2024). "Resveratrol, a known SIRT1 activator, also attenuated IL-5 and IL-13 as well as eosinophil accumulation in ovalbumin-induced allergic rhinitis in mice." (PMID 32823491, 2020). "In a mouse model of OVA-induced allergic rhinitis, SIRT1 administration reduced symptoms such as sneezing and nasal rubbing events, and it led to a significant reduction in serum IgE." (PMID 32823491, 2020). "Furthermore, SIRT1 expression was enhanced, leading to a mitigation of allergic rhinitis symptoms." (PMID 39081309, 2024). "In addition, many studies have demonstrated the potential role of resveratrol in the treatment of allergic rhinitis, as it can effectively alleviate AR in mice by inhibiting the oxidative stress pathway of TXNIP, and its mediated activation of SIRT1 also attenuates ovalbumin-induced ARin mice." (PMID 41105646, 2025).
aortic aneurysm (4 papers, 2019 to 2025). A ruptured aneurysm located in the wall of the proximal portion of the descending aorta proceeding from the arch of the aorta. "In a study exploring the effects of calorie restriction on AAA development, Sirtuin 1 (SIRT1) expression in VSMCs was found critical for mediating the protective effects of calorie restriction against aortic aneurysm formation." (PMID 35207478, 2022). "In this review, we will focus on yet another role of SirT1 in vascular disease, namely aortic aneurysm, which only recently started to be appreciated." (PMID 32982786, 2020). "Specifically, we describe recent research advances on SirT1-mediated molecular mechanisms in aortic aneurysm (AA), and how these processes relate to oxidant stress and the heme-oxygenase (HO) system." (PMID 32982786, 2020). "Ablation of the antisenescence gene SIRT1 in VSMCs promotes aortic aneurysm formation induced by Ang II in Apoe−/− mice, while overexpression of SIRT1 in VSMCs has the opposite effect." (PMID 31147528, 2019).
Aortic dissection (4 papers, 2019 to 2026). Aortic dissection refers to a tear in the intimal layer of the aorta causing a separation between the intima and the medial layers of the aorta. "Contrary to the literature, it was found that high SIRT1 levels were associated withtype A aortic dissections." (PMID 41259217, 2026). "Type A aortic dissections are associated with elevated SIRT1 levels in thetissue." (PMID 41259217, 2026). "In Fang Wang's study, they administered a chemical that induces thoracic aorticaneurysm (TAA) and aortic dissection in mice and compared mice with high and lowlevels of smooth muscle-specific SIRT1." (PMID 41259217, 2026). "Thiscontrasts with the notion that SIRT1 elevation is protective against ascendingaortic aneurysms and aortic dissection, as suggested in the literature." (PMID 41259217, 2026). "Many genes, such as YAP1, Sirtuin-1, PCSK9, polycystin-1, and brahma-related gene 1, have also been reported to be associated with the pathophysiologic processes of aortic dissection by influencing the proliferation and migration of VSMCs." (PMID 31751374, 2019). "However, contrary to this example, our studydemonstrated that patients with aortic dissection had higher SIRT1 levels comparedto the control group." (PMID 41259217, 2026). "Therefore, our research suggests that miR‐485‐3p can aggravate inflammation and apoptosis in vascular smooth muscle cells by suppressing the expression of SIRT1, thereby promoting the progression of aortic dissection." (PMID 39010253, 2024).
Arterial thrombosis (4 papers, 2018 to 2023). The formation of a blood clot inside an artery. "More recently, the interplay between SIRT1 and tissue factor was confirmed in a study aimed to investigate the effect of chronic exposure to indoxyl sulfate on the hemostatic system and arterial thrombosis in a rat model." (PMID 38304233, 2023). "Taken together, our data suggest that by enhancing autophagy flux and decreasing the release of vWF and P-selectin, the Sirt1/FoxO1 pathway may be a promising target to prevent AS and arterial thrombosis." (PMID 31450612, 2019). "Then, we measured the expression of Sirt1, an important modulator of TF and arterial thrombosis." (PMID 30347685, 2018). "We confirmed that IS-induced arterial thrombosis after chronic administration increased the kinetics and strength of clot formation, and contributed to platelet hyperactivity as well as reduced aortic levels of SIRT1 and SIRT3." (PMID 30546314, 2018). "Sirt1/FoxO1 may be a potential target to prevent the development of AS and arterial thrombosis." (PMID 31450612, 2019). "This study demonstrates that IS promotes arterial thrombosis and prothrombotic state that is connected with an increased level of complex TF/VII, PAI-1, and platelet activation, as well as decreased aortic contents of SIRT1 and SIRT3." (PMID 30546314, 2018).
bone metabolism disorders (4 papers, 2018 to 2025). "A comprehensive understanding of SIRT1's regulatory mechanisms will facilitate a deeper exploration of the principles underlying exercise-induced improvements in bone metabolism, ultimately providing novel insights into the treatment of bone metabolic disorders." (PMID 40206398, 2025). "In conclusion, decreased serum Sirtuin 1 levels are associated with bone turnover markers in T2DM patients and may serve as an independent risk factor and potential biomarker for diagnosing bone metabolism disorders in newly diagnosed T2DM patients." (PMID 39944232, 2024). "We also examined microRNA-132 (miR-132), a regulator in the Sirtuin1 (Sirt1) expression.The bone metabolism disorder, bone morphology, BMD, and bone biomechanics in ovariectomized rats were improved by EZP administration.The antiosteoporotic effect of EZP was confirmed." (PMID 30224934, 2018).
brain tumors (4 papers, 2020 to 2025). "Several studies have analyzed SIRT1 in association with various types of brain tumors." (PMID 34942940, 2021). "Given its established pathological significance in brain tumors, SIRT1 critically contributes to MGM pathogenesis." (PMID 41208649, 2025). "Recently, an increasing number of reports have shown that SIRT1 plays an important role in brain tumors." (PMID 32158616, 2020). "An increasing number of reports have indicated that SIRT1 plays an important role in controlling brain tumors." (PMID 32158616, 2020). "Although the molecular mechanisms linking AMPK signaling involving SIRT1 and AKT with CSPGs is still elusive, a prior study suggested the AMPK signaling induced regulation of CSPGs in brain tumor." (PMID 35892563, 2022). "Overall, our results suggest that SIRT1 and AROS inhibit GSK3β activity and provide a basis for the mechanism of DOX efficacy in brain tumor chemotherapy." (PMID 32158616, 2020).